ALB (albumin)
Diseases named in the same sentence as ALB in open-access papers (continued):
Sharing a sentence is not in itself a finding about the gene and the disease.
Failure to thrive (3 papers, 2020 to 2023). Failure to thrive (FTT) refers to a child whose physical growth is substantially below the norm. "We recommend using albumin infusions based on clinical indicators of hypovolaemia (including oliguria, acute kidney injury, prolonged capillary refill time, tachycardia, hypotension and abdominal discomfort) or upon failure to thrive." (PMID 33514942, 2021). "Others may need frequent albumin infusions to prevent the clinical consequences of hypovolaemia and failure to thrive." (PMID 33514942, 2021). "We recommend basing the use of albumin infusions on clinical indicators of hypovolaemia or on failure to thrive, rather than on serum albumin levels." (PMID 33514942, 2021).
Fanconi syndrome (3 papers, 2012 to 2024). "However, nephron segments downstream of the proximal convoluted tubules can reabsorb about 26% of glomerular filtrated albumin even if proximal tubular albumin reabsorption is impaired in Fanconi syndrome." (PMID 22685655, 2012). "The fractional excretion of albumin in Fanconi syndrome patients is 0.00008, and this may be approximately equivalent to the glomerular-sieving coefficient in the normal kidney." (PMID 22685655, 2012).
fetal hydrops (3 papers, 2022 to 2025). "The initial diagnosis time, gestational age at birth, birthweight, Apgar score, and initial albumin and pH levels were the independent factors associated with fetal hydrops mortality." (PMID 35455574, 2022). "We report two cases, one preterm and one term neonate, both presenting with features of CNS and hydrops fetalis, who demonstrated spontaneous normalization of serum albumin levels and urine protein-to-creatinine ratio within a few weeks of life." (PMID 41246647, 2025). "We also collected information regarding disease etiology, duration of hospital stay, Apgar score, gestational age at birth, initial hydrops fetalis diagnosis, fetal intervention, first albumin and pH levels, and maternal history." (PMID 35455574, 2022). "The serum albumin concentration was considered to be closely correlated with the severity of hydrops fetalis." (PMID 35455574, 2022).
fibrosarcoma (3 papers, 1971 to 2022). A malignant mesenchymal fibroblastic neoplasm affecting the soft tissue and bone. "Albumin distributions and turnover rates have been studied using 131I labelled tracer material in rabbits with Vx2 carcinoma and rats bearing SP7 fibrosarcoma in comparison with control animals." (PMID 5115834, 1971).
follicular lymphoma (3 papers, 2014 to 2025). Follicular lymphoma is a form of non-Hodgkin lymphoma characterized by a proliferation of B cells whose nodular structure of follicular architecture is preserved. "Several studies have reported higher risk of transformation in patients with advanced disease stage, presence of B symptoms and bulky disease, high β2 microglobulin and low albumin levels, and higher scores of follicular lymphoma international prognostic index." (PMID 25161781, 2014).
frontotemporal dementia (3 papers, 2016 to 2024). Frontotemporal dementia (FTD) comprises a group of neurodegenerative disorders, characterized by progressive changes in behavior, executive dysfunction and language impairment, as a result of degeneration of the medial prefrontal and frontoinsular cortices. "BBB disruption increases albumin levels in the cerebrospinal fluid (CSF) and the brains of elderly and the patients with Alzheimer’s disease (AD), frontotemporal dementia (FTD) or other neurodegenerative disease patients." (PMID 38654316, 2024).
gastric atrophy (3 papers, 2020 to 2025). "This retrospective study found that age; successful H. pylori eradication; and laboratory data, including ALT, ALP, albumin, HbA1c, UA, Fib4 index, DM, HT, and DL, were significantly associated with the endoscopic gastric atrophy grade." (PMID 38804394, 2024). "Age, successful H. pylori eradication, and laboratory data, including ALT, ALP, albumin, HbA1c, UA, Fib4 index, DM, HT, and DL, were significantly associated with the endoscopic gastric atrophy grade." (PMID 38804394, 2024). "On the other hand, the presence of atrophic gastritis was correlated only with physiological markers such as albumin and total protein levels measured preoperatively." (PMID 41007784, 2025). "Demographic, clinical, and endoscopic data including body mass index (BMI), serum albumin and cholesterol, gastric atrophy, reflux oesophagitis, Barrett’s oesophagus, and H. pylori status were collected." (PMID 32843976, 2020).
glucosuria (3 papers, 2015 to 2023). "Urine analysis showed also glucosuria and increased potassium, sodium, creatinine, uric acid, and albumin levels." (PMID 25629046, 2015). "We found that tight regulation of mTORC1 activity seems to be essential for physiological tubular transport functions: both mTORC1 activation (Tsc1 deletion) and inhibition (Raptor deletion) induced glucosuria and increased urinary KIM-1 and albumin excretion." (PMID 32726619, 2020).
HELLP syndrome (3 papers, 2014 to 2022). A life-threatening condition that can potentially complicate pregnancy. "By multivariate analysis, the only independent factors were the association of HELLP syndrome with postpartum haemorrhage and the use of hyperoncotic albumin infusion." (PMID 25593752, 2014). "The only independent risk factors identified were the association of postpartum hemorrhage with the HELLP syndrome (OR [CI 95%] = 4.1 [1.75 to 9.66]; p = 0.0012) and the administration of 20% hyperoncotic serum albumin (OR [CI 95%] = 3.34 [1.47 to 7.60]; p = 0.0039)." (PMID 25593752, 2014).
helminth infection (3 papers, 2012 to 2022). "Helminthic infections cause a decrease in albumin and increase in globulin." (PMID 23109947, 2012). "The finding of lower albumin (and by association, calcium) among individuals with HIV and helminth infections in this study is therefore reasonable." (PMID 36501001, 2022).
Hematemesis (3 papers, 2022 to 2023). The vomiting of blood. "In this study, through multivariate analysis, we identified several factors, including SBP < 100 mm Hg, heart rate > 100 beats/minutes, hematemesis, and albumin level < 3.0 g/dL." (PMID 37653832, 2023). "Multivariate analysis revealed that SBP < 100 mm Hg, heart rate > 100 beats/minutes, hematemesis, and albumin level < 3.0 g/dL were related to rebleeding." (PMID 37653832, 2023). "In addition, patients who received FFP transfusion were more likely to have hematemesis, and their admission systolic blood pressure, hemoglobin, and albumin average were lower than those who did not receive FFP transfusion." (PMID 35911402, 2022).
Hematochezia (3 papers, 2023 to 2024). The passage of fresh (red) blood per anus, usually in or with stools. "Several studies have shown that early onset of acute gastrointestinal GVHD, severe clinical gastrointestinal GVHD, hematochezia, mismatched donor type, and low albumin and high serum bilirubin levels are risk factors for mortality in patients with gastrointestinal GVHD." (PMID 37614955, 2023).
Hepatic cysts (3 papers, 2016 to 2024). "We also found that the presence of hepatic cysts was associated with the following laboratory variables; lower serum albumin, lower serum GGT, lower serum uric acid, higher LDL-cholesterol, lower glucose, and lower systolic blood pressure." (PMID 35896780, 2022). "The present study also demonstrated that renal and hepatic cysts were more common in patients with spinal involvement, and their serum creatinine, albumin-globulin ratio, and liver transferase levels differed significantly from those of patients without spinal involvement." (PMID 39035571, 2024). "When the participants were divided into three groups according to serum albumin levels, the prevalence of hepatic cysts was significantly higher in the group with low albumin levels: 17.5% for albumin ≥ 4.6 g/dl, 22.0% for albumin 4.3–4.5 g/dl, and 25.1% for albumin ≤ 4.2 g/dl, respectively." (PMID 35896780, 2022). "Among these, the albumin level was a strong predictor for hepatic cysts." (PMID 35896780, 2022). "Foetal HPCs can form hepatic cysts characterized by Albumin-positive/CK19-negative in vitro." (PMID 27881141, 2016).
hyperemesis gravidarum (3 papers, 2021 to 2026). Severe, intractable vomiting during pregnancy (usually the first trimester) accompanied by dehydration, weight loss, and electrolyte imbalances. "This study aimed to evaluate the diagnostic utility of the albumin/lymphocyte ratio (ALR) and mean platelet volume/lymphocyte ratio (MPVLR) novel inflammatory markers not previously studied in hyperemesis gravidarum (HG) as potential biomarkers in patients diagnosed with HG." (PMID 41316928, 2025). "We believe that our study results are important for adding Albumin/Lymphocyte ratio and MPV/Lymphocyte ratio, which have not been previously investigated in hyperemesis gravidarum patients, to the literature." (PMID 41316928, 2025).
hyperplasia (3 papers, 2020 to 2022). An abnormal increase in the number of cells in an organ or a tissue with consequent enlargement. "In addition, the mechanism responsible for low platelet and albumin levels in patients with recurrent gastric mucosal atypical hyperplasia requires further exploration and clarification." (PMID 36344959, 2022).
Incisional hernia (3 papers, 2023 to 2024). An abdominal hernia that occurs at a site of weakness in the abdominal wall resulting from an incompletely-healed surgical wound. "In our study, an albumin level < 3.4 gr/dL, BMI ≥ 30 kg/m2, and abdominal wall dehiscence were significant risk factors for incisional hernia formation following PD, and the outcome of incisional hernia was not influenced by the incision performed and suturing technique." (PMID 37622995, 2023).
infectious peritonitis (3 papers, 2024 to 2025). Inflammation of the peritoneum due to infection by bacteria or fungi. "Similarly, in cats with infectious peritonitis (FIP), alpha − 2, beta-, and gamma-globulin levels were significantly higher and albumin levels were lower than those in healthy cats." (PMID 39085867, 2024).
Inguinal hernia (3 papers, 2023 to 2026). Protrusion of the contents of the abdominal cavity through the inguinal canal. "To ensure that the selected single-nucleotide polymorphisms (SNPs) remained unrelated to any confounding factors influencing the association between ALB and inguinal hernia, we specifically included participants from European populations." (PMID 38591204, 2024). "We assessed the causal association between ALB levels and inguinal hernia." (PMID 38591204, 2024). "Serum ALB levels might be causally associated with an increased risk of inguinal hernia." (PMID 38591204, 2024). "The correlation between the ALB gene and inguinal hernia was subsequently validated through a two-sample Mende randomization." (PMID 38591204, 2024). "In summary, this study suggests that ALB holds promise as a potential therapeutic target for addressing inguinal hernia." (PMID 38591204, 2024). "The 5 negative predictors with the strongest association with the primary outcome were measurement values of albumin, prothrombin time, PR interval, condition of “inguinal hernia,” and drug of azelastine." (PMID 37955965, 2023). "Over the subsequent four months, her serum albumin levels increased, intradialytic hypotension resolved, and the ascites subsided without recurrence, thus permitting the repair of an inguinal hernia identified at referral." (PMID 41944989, 2026). "This implies that there was no dominant SNP influencing ALB levels and inguinal hernia, confirming the validity of the previous MR results." (PMID 38591204, 2024).
insulinoma (3 papers, 2018 to 2022). "The patients with insulinoma had lower average blood glucose levels, as suggested by lower hemoglobin A1c and glycated albumin (%), than controls." (PMID 36339408, 2022). "Indices of glycemic control, hemoglobin A1c (HbA1c) and glycated albumin (GA) may be useful for screening patients with insulinoma having chronic hypoglycemia because the values become low in such a condition while no relevant information has been reported." (PMID 30808334, 2019). "Indices of glycemic control, hemoglobin A1c (HbA1c), and glycated albumin (GA) may be useful for the screening of patients with insulinoma having chronic hypoglycemia because the values become low in such a condition." (PMID 30808334, 2019).
intracranial aneurysm (3 papers, 2018 to 2025). "We thus investigated whether preoperative albumin level is associated with postoperative AKI in patients after cerebral artery aneurysm clipping surgery." (PMID 30395651, 2018). "Although AKI has been reported as an independent predictor of outcomes after aneurysmal subarachnoid hemorrhage, the influence of serum albumin on postoperative AKI development following cerebral artery aneurysm clipping has not been studied." (PMID 30395651, 2018).
kidney transplant (3 papers, 2021 to 2024). A surgical procedure in which one or both kidneys from a donor are implanted into a recipient. "In the early posttransplant period, kidney transplant recipients lost muscle mass, gained fat mass, and developed mostly negative SPhA, accompanied by significantly lower albumin levels." (PMID 35252294, 2022). "Important variables in the RF models for acute rejection among Black kidney transplant recipients included recipient age, ESKD etiology, PRA, cold ischemia time, donor age, HLA DR mismatch, BMI, serum albumin, degree of HLA mismatch, education level, and dialysis duration." (PMID 34822363, 2021).
Kidney tumor (3 papers, 2021 to 2023). "ICG, a water-soluble compound that binds to plasma albumin, emits near-infrared light, enabling the visualization of kidney vasculature and renal tumors." (PMID 38067266, 2023). "ICG, a water-soluble molecule binding to plasma albumin, emits light in the near-infrared spectrum, enabling the visualization of kidney vasculature and renal tumors." (PMID 38067266, 2023).
kwashiorkor (3 papers, 2015 to 2022). A syndrome produced by severe protein deficiency, characterized by retarded growth, changes in skin and hair pigment, edema, and pathologic changes in the liver, including fatty infiltration, necrosis, and fibrosis. "It has been argued that the oedema of kwashiorkor is not caused byhypoalbuminaemia because the oedema disappears with dietary treatment before theplasma albumin concentration rises." (PMID 25223408, 2015).
laryngeal squamous cell carcinoma (3 papers, 2017 to 2025). A squamous cell carcinoma that arises from the larynx. "This retrospective study aims to analyze the efficacy and safety of PD-1 inhibitors combined with albumin-bound paclitaxel and cisplatin in the treatment of recurrent or metastatic hypopharyngeal/laryngeal squamous cell carcinoma." (PMID 38827739, 2024). "This retrospective study analyzed the efficacy of PD-1 inhibitors combined with albumin-bound paclitaxel and cisplatin (TP regimen) in the treatment of recurrent and metastatic hypopharyngeal/laryngeal squamous cell carcinoma (RMHSCC/RMLSCC)." (PMID 38827739, 2024). "This study evaluated the predictive value of the preoperative albumin/globulin ratio (AGR) in laryngeal squamous cell carcinoma (LSCC) retrospectively, which has not been reported before." (PMID 28654895, 2017).
Lowe syndrome (3 papers, 2015 to 2025). "Similar results have been observed in renal proximal tubular dysfunction in Lowe syndrome (LS), in which a stall of megalin is observed in early endosomes associated with a decrease in surface megalin expression and albumin endocytosis." (PMID 35055044, 2022). "CLCN5 encodes the electrogenic chloride/proton exchanger ClC-5 which is involved in the tubular reabsorption of albumin and LMW proteins, OCRL encodes the inositol polyphosphate 5-phosphatase, and was initially associated with Lowe syndrome." (PMID 26389017, 2015). "Whether abnormal glomerular filtration may contribute to albuminuria in late stages of CKD in Lowe syndrome is unknown, but increased albumin filtration is unlikely to cause significant further injury to an already dysfunctional proximal tubule." (PMID 41278199, 2025). "All Lowe syndrome patients have albuminuria/proteinuria and more than half have proteinuria in the nephrotic range >1 g/m2/day; however, serum albumin remains normal to mildly elevated and is never low." (PMID 41278199, 2025).
macrophage activation syndrome (3 papers, 2021 to 2024). A complication of rheumatic disease that is caused by excessive activation and uncontrolled proliferation of T lymphocytes and well-differentiated macrophages. "Myelogram resulted in conjunction with hypergammaglobulinemia and hypoalbuminemia (serum albumin: 32 g/L), suggesting macrophage activation syndrome (MAS)." (PMID 39194726, 2024).
malignant pleural mesothelioma (3 papers, 2016 to 2021). A malignant neoplasm that arises from mesothelial cells in the pleura and shows a diffuse growth pattern. "Yoshida N, Baba H. The C-reactive protein/albumin ratio may predict the long-term outcome in patients with malignant pleural mesothelioma." (PMID 33331459, 2021).
murine typhus (3 papers, 2012 to 2022). "Laboratory parameters outside the normal range that differed between the two forms of typhus were plasma albumin, C-reactive protein (CRP) and lactate dehydrogenase." (PMID 26317419, 2015). "Laboratory parameters that differed between the two typhus groups were plasma sodium, creatinine, albumin, C-reactive protein (CRP) and lactate dehydrogenase, although sodium and creatinine values remained within the normal range for both groups." (PMID 22192733, 2012). "A minority of patients required respiratory support (35, 6.2%), albumin transfusion (26, 4.7%) or dialysis (3, 0.5%), and no statistical differences were observed between scrub and murine typhus groups." (PMID 35736967, 2022).
muscle atrophy (3 papers, 2023 to 2025). The loss of muscle tissue due to inactivity or disease. "It has been found that higher serum albumin concentrations are associated with protective effects against skeletal muscle atrophy, decreased gait speed, and the occurrence of muscle wasting." (PMID 36771359, 2023). "Muscle atrophy may lead to branched-chain amino acid metabolic dysregulation, which is closely associated with hepatic albumin synthesis and hematopoietic function." (PMID 40507924, 2025).
Mycoplasma infection (3 papers, 2017 to 2024). "Lower serum albumin concentration and A:G ratio in cats with feline hemotropic mycoplasmosis compared to healthy cats can be interpreted as an inflammatory response due to infection and acute phase response." (PMID 38839816, 2024). "Lactate, TBil, DBil, AST, LDH, and P levels of cats with hemotropic mycoplasmosis were significantly higher than healthy cats, but albumin and A:G ratio were lower (p < 0.05)." (PMID 38839816, 2024). "Elimination of Mycoplasma infection restored the levels of ALB, TF, and CYP3A4 genes as well as proteins to normal levels." (PMID 29075618, 2017). "In the present study, albumin and A:G ratio were significantly lower in cats with feline hemotropic mycoplasmosis compared to healthy cats and were found to be good prognostic indicators for predicting mortality with 92% sensitivity and 88% specificity at a cut-off point of 0.46 ng/mL." (PMID 38839816, 2024). "Besides, a growing body of evidence have shown that SLC8A1, male, infants < 6 months old, low serum albumin, high ESR, CRP, mycoplasma infection, IVIG started after the 10th day of illness and IVIG non-responders may increase the risk of CAA." (PMID 31366406, 2019).